IL6 (interleukin 6)
Diseases named in the same sentence as IL6 in open-access papers (continued):
Sharing a sentence is not in itself a finding about the gene and the disease.
lupus (continued). "In systemic lupus erythematosus, increased interleukin-6 (IL-6) activity, overstimulation of T- and B-cells, coupled with defects in the immune system's surveillance system may increase the risk of cancer." (PMID 35220046, 2022). "Interestingly, B-cell-derived IL-6 initiates spontaneous autoimmune germinal center formation in Lupus-prone mice." (PMID 35589797, 2022). "In addition, it has been reported that macrophage-derived IL-6 has a prominent role in promoting anti-DNA autoantibodies in lupus-prone BWF1 mice." (PMID 35211864, 2022). "Furthermore, B cell derived IL-6 drives spontaneous germinal centre formation in murine lupus, thus, providing a mechanism by which excessive IL-6 production by B cells can result in autoantibody production and autoimmunity." (PMID 36726987, 2022). "Moreover, TNF-α and IL-6 are also important for lupus exacerbation as the potent pro-inflammatory cytokines in macrophage and neutrophil activation." (PMID 35897790, 2022). "This protective effect seems to be associated with the significantly decreased production of IL-6 and TNF-α, indicating that abnormally activated autophagy in macrophages may contribute to lupus by promoting the production of TNF-α and IL-6." (PMID 35456038, 2022). "More importantly, we could show that both IFN-γ and IL-6, two cytokines involved in lupus pathogenesis, significantly down-regulated Trap1 expression in spleen cells after in vitro culture, whereas no change was observed with IFN-α or IL-17A." (PMID 33746957, 2021). "Previous studies have suggested that positive RF frequently coexists with elevated concentration of inflammatory markers, such as CRP, procalcitonin (PCT) and interleukin-6 (IL-6) in patients with Sjogren’s syndrome, systemic lupus erythematosus, RA and viral hepatitis." (PMID 34543280, 2021). "B cell–specific deletion of IL-6 has been shown to reduce serum IL-6 in another lupus model." (PMID 34197340, 2021). "Importantly, the inhibition of HA in lupus-prone mice improved disease parameters, at least partially by reducing the expression of pro-inflammatory cytokines, including IL-1β, TNFα, and IL-6, in the kidney." (PMID 33240280, 2020). "The expressions of TNF-α and IL-6 in lupus patients are generally higher than that in healthy people, and studies have reported that the lack of IRAK1 could reduce the production of IL-6 and TNF-α." (PMID 32760274, 2020). "Given the highly inflammatory milieu of female NWB/NZW F1 mice, including elevated levels of serum GM-CSF, IL-6, and IFNα, it is possible that naturally occurring MDSCs in female lupus-prone mice are induced to differentiate into effector cells with an immune-stimulatory phenotype." (PMID 32655565, 2020). "Treatment with polyclonal anti-IL-6 or anti-IL-6 receptor monoclonal antibodies could inhibit IL-6 binding and suppressed total IgG and IgG anti-ssDNA antibody secretion in lupus B cells." (PMID 31835612, 2019). "Interestingly, blocking NEU inhibited IL-6 production in the mesangial cells of MRL/lpr lupus-prone mice." (PMID 31137925, 2019). "Moreover, TLR2-deficiency significantly reduced anti-DNA/nucleosome antibodies, renal disease, and IL-6 production in a pristane-induced lupus mouse model." (PMID 31354738, 2019). "Serum IL-6 levels are elevated and correlated with disease activity in patients with lupus." (PMID 30547812, 2018). "Interestingly, the study did note that lupus patients with poorer cognitive function had higher circulating levels of interleukin-6 (IL-6)." (PMID 28853005, 2018). "CX3CR1- and CD103-expressing cells are primarily APC that can capture bacteria from the gut lumen and transport them to the MLN, where they present antigens and activate CD4+ T cells to produce IL-6 that suppresses Treg, which is vital to lupus pathogenesis in lpr mice." (PMID 28697806, 2017). "The study of lupus mice demonstrated that IL-6 is involved in the pathogenesis disease." (PMID 28286780, 2017).
lupus (continued). "The application of HDAC inhibitors, such as trichostatin A (TSA), leads to a wide-ranged acetylation of histones and thus reduces the expression level of those inflammatory cytokines, such as IL-2, interferon (IFN)-γ, and IL-6, as well as alleviate the symptoms of lupus-prone mice." (PMID 28785369, 2017). "Other studies have already established direct interactions between DCs and B cells in the context of lupus, where DCs from an autoimmune context are capable of increasing B cell effector functions dependent on soluble factors, such as IL-6 and IFN-γ, and also through direct cell-to-cell contact." (PMID 28741259, 2017). "Furthermore, LPS-activated BMDC from lupus-prone mice suppressed Treg function by producing more IL-6, which indirectly promoted proliferation of CD4+ T cells." (PMID 27034965, 2016). "In line with this hypothesis, the methylationlevel of the IL-6 promoter has been reported to be significantly correlated to thedevelopment and the severity of systemic lupus erythematosus." (PMID 27627640, 2016). "Finally, inhibition of select DLK1-Dio3 miRNA such as miR-154, miR-379 and miR-300 with specific antagomirs significantly reduced the production of lupus-relevant IFNγ, IL-1β, IL-6, and IL-10 in lipopolysaccharide (LPS) activated splenocytes from MRL-lpr mice." (PMID 27070142, 2016). "In addition, it was shown that lymphoblastoid B cells isolated from lupus patients produced increased levels of IL6." (PMID 27050763, 2016). "It has been demonstrated in lupus-prone mice that IL-6 produced by DCs inhibits Tregs, because Foxp3+ Treg cells lose Foxp3 expression and undergo conversion into Th17 cells under the effect of IL-6." (PMID 27852285, 2016). "Furthermore, accumulated RP105− B lymphocytes with ANAs and IL6 production are also observed in lupus-prone NZB/W F1 mice." (PMID 26068236, 2015). "Our finding that MRL/lpr DC produced lower basal and LPS-induced levels of IL-6 is in accordance with a previous study showing that DC from lupus mice, including MRL/lpr and MRL/mpj, produce lower levels of IL-6 in response to several toll-like receptor (TLR)-ligands." (PMID 25886192, 2015). "Lupus-associated and inflammatory cytokine genes, such as IL4, IL6, IL10 and IL13, are demethylated in lupus T cells and may contribute to disease progression." (PMID 25988383, 2015). "However, activating TLR7 by CL095 together with co-activation of BCR can promote IL6 production by B cells, especially in B cells from lupus-prone mice." (PMID 26068236, 2015). "However, under anti-inflammatory conditions the TC lupus background cannot efficiently repress production of IL-6 by MZ B cells." (PMID 25093822, 2014). "For example, polymorphisms of the interleukin 6 gene, a stimulator of inflammatory plasma proteins, have shown association with intracranial aneurysm prevalence and an increased risk of SAH has been found in patients with systemic lupus erythematosus." (PMID 24708536, 2014). "Studies in lupus-prone mice support an important role for IL-6 in evoking autoimmune sequelae." (PMID 24945254, 2014). "Since serum levels of IL-6 have been described to correlate with disease activity in both systemic lupus erythematosus and BP, further studies of a more detailed analysis of the possibly pathophysiologically relevant IL-6-Hsp90 interplay in BP patients are warranted." (PMID 23936217, 2013). "Consistent with above results in vitro, MBL treatment could suppress the pro-inflammatory cytokine TNF-α, MCP-1 and IL-6 while increase the expression of IL-10 in the renal macrophages and in serum of lupus mice." (PMID 23626823, 2013). "Importantly, this study demonstrates the beneficial effects of cystamine on inducing antioxidant activities and CD4+/CD25+ regulatory T cells in lupus-prone mice by decreasing IL-6/STAT3 signalling." (PMID 23905628, 2013).
lupus (continued). "Infiltrating mononuclear cells are the major source of IL-6 in diseased kidneys affected by lupus nephritis, IL-6 can in return promote macrophage activation, it is elevated in the serum and urine of some lupus patients, and murine lupus models support a role for IL-6 in nephritis." (PMID 22701502, 2012). "On the other hand, increased IL-6 promotes antibody production in humans and mice with lupus." (PMID 22701487, 2012). "Mice with epidermal loss of JunB reportedly developed an SLE phenotype linked to increased epidermal IL-6 secretion, and facial skin biopsies of SLE patients displayed low levels of JunB protein expression, high IL-6, and activated STAT3 levels within lupus lesions." (PMID 22315615, 2012). "Moreover, infusion of an antibody to IL-6 can relieve disease symptoms in lupus-prone NZB/NZW F1 mice." (PMID 21152185, 2011). "A 1990 investigation using NZB/W F1 mice, an animal model of systemic lupus erythematosus (SLE), revealed a potential involvement for IL‐6 in the immune complex‐mediated glomerulonephritis pathogenesis." (PMID 40976999, 2025). "For instance, in the circumstances of autoimmune diseases (systemic lupus erythematosus [SLE] and RA) or AD, B cells are driven to differentiate into age‐related phenotype by abnormally accumulated proinflammatory factors such as IL‐6 and TNF‐α." (PMID 41427020, 2025). "Consistent with our hypothesis, Acod1−/− mice exposed to a TLR7 agonist, a lupus relevant stimulus, displayed disruptions in the splenic architecture, increased serum anti-dsDNA and IL-6, higher kidney immune complex deposition and proteinuria, when compared to the WT IMQ-treated mice." (PMID 38605883, 2024). "Since IL-6 has been implicated in the pathophysiology of Systemic Lupus Erythematosus (SLE), effects of IL-6 blockade used to treat the disease have been studied in patients with Lupus GN as well." (PMID 39723211, 2024). "Higher concentrations of IL-6 are found in serum of SLE patients compared to control individuals which correlated with SLEDAI (systemic lupus erythematosus disease activity index) or anti-DNA levels." (PMID 33776578, 2021). "During SARS-CoV-2 infection, the type I interferon (IFN) and IL-6 synthesis are dysregulated in myeloid cells, resembling the type I IFN signature in systemic lupus erythematosus (SLE) and the IL-6-mediated macrophage activation syndrome." (PMID 34685525, 2021). "B cells have been identified as major producers of IL-6 in disease models for systemic lupus erythematosus (SLE) and multiple sclerosis (MS)." (PMID 34054864, 2021). "While LPS tolerance affected only TNF-α and IL-6 production in wild-type macrophages, LPS tolerance also impaired other pathogen control mechanisms (phagocytosis and microbicidal activity) in FcGRIIb−/− cells as a mechanism possibly responsible for the significant LPS exhaustion in lupus." (PMID 30889825, 2019). "There is evidence that interleukin-6 (IL-6) upregulation plays a critical role in immunopathology of systemic lupus erythematosus (SLE)." (PMID 31886314, 2019). "In a model of lupus nephritis, the HDAC inhibitor ITF2357 diminished the proinflammatory gene expression of il6, il-1β, and the systemic lupus erythematosus (SLE) serum biomarker IgG2a." (PMID 30647531, 2018). "Besides, the positive correlation between serum IL-6 levels and autophagosome levels in circulating lymphocytes is in agreement with the previous finding that the knockdown of autophagic initiation ameliorates activated lymphocyte-derived DNA-induced murine lupus through an inhibition of IL-6." (PMID 30518408, 2018). "The observation that high IFN-I production by this cytosolic pathway is not sufficient to elicit autoimmunity suggests that TLRs may be more efficient in the induction of other proinflammatory molecules, including IL-6 known to promote lupus in mice and humans." (PMID 30199535, 2018).
lupus (continued). "In systemic lupus erythematosus (SLE) patients and mice, the concentration of IL-6 is elevated in serum, urine, and glomeruli, which positively associated with disease activity." (PMID 28484449, 2017). "The serum IL-6 levels were variable, and levels were higher depending on SLE manifestations such as lupus nephritis." (PMID 29445400, 2017). "Recently, studies have revealed that there is a link between PBMC IL-6 expression level and lupus disease activity as compared to the IL-6 expression in PBMCs from SLE patients and healthy control." (PMID 28785369, 2017). "Elevated serum levels of IL6 correlate with disease flares in patients with systemic lupus erythematosus (SLE)." (PMID 27050763, 2016). "For example, IL-6 levels increased in response to a cold pressor task in patients with RA and juvenile idiopathic arthritis, but IL-6 and IFNγ levels remained unchanged after psychological stress was induced in patients with RA and systemic lupus erythematosus." (PMID 24274618, 2013). "IL-6 can target IFN-inducible genes such as Ifi202 in murine fibroblasts and splenocytes through activation of STAT3, which results in the suppression of cell cycle progression and inhibition of apoptosis, thereby contributing to increased lupus susceptibility." (PMID 24171032, 2013). "In addition, lupus B lymphocytes are hypersensitive to IL-6." (PMID 23140401, 2012). "Urinary excretion and renal expression of IL-6 was elevated in SLE patients with active proliferating lupus nephritis, as were IL-6 levels in the cerebrospinal fluid of SLE patients with central nervous system involvement." (PMID 22315615, 2012). "Aberrant IL-6 expression or signaling contributes to numerous diseases, including inflammatory and lymphoproliferative disorders such as giant cell arteritis, multiple myeloma, rheumatoid arthritis, and systemic lupus erythematosus (SLE)." (PMID 41281572, 2025). "Additionally, patients with SLE or lupus nephritis have higher serum and urine IL‐6 concentrations, which are correlated with disease activity." (PMID 40976999, 2025). "The three Lactobacillus strains improved hepatic injuries and reduced inflammation in lupus-prone mice by suppressing MAPK/NF-κB signaling pathways and lowering IL-1β, IL-6, and TNF-α expression." (PMID 40534849, 2025). "Other emerging agents, including IL-6,IL-1β, and BTK inhibitors, aim to reduce inflammation-driven CVD, echoingfindings from non-lupus trials like CANTOS." (PMID 41356287, 2025). "Our gene expression analyses show induction of inflammatory pathways in tRCC, including IFN-γ response, IL-6/JAK/STAT3, TLR signaling, immunoglobulin-mediated phagocytosis, systemic lupus erythematosus, NK cell–mediated cytotoxicity, and allograft rejection." (PMID 38386415, 2024). "Some of the more recent failures in lupus trials include anti-CD20 (rituximab), anti-CD22 (epratuzumab), anti-BAFF (tabalumab, atacicept) CD28-Fc (abatacept), anti-IL6 (PF-04236921), and anti-IFN-α (sifalimumab)." (PMID 39452087, 2024). "Purified human CD4+ T cells stimulated with anti-CD3 and anti-CD28 antibodies exhibited robust production of lupus-related pro-inflammatory cytokines (e.g., IFN-γ, TNF-α, IL-5, and IL-6) upon anti-CD3/CD28 beads stimulation." (PMID 39551768, 2024). "In patients with systemic lupus erythematosus (SLE), IL-6 potentiates the activity of autoreactive B cells." (PMID 37298597, 2023). "Increased levels of miR-146a are related to the inhibition of pro-inflammatory cytokine production (IL-6, TNF-α, and IL-1β) and the expression of inflammatory mediators, leading to the survival of lupus-prone mice." (PMID 37372034, 2023). "In a study on pristane-induced lupus in BALB/c mice, baicalin reduced the production of proinflammatory cytokines such as TNF-α, IL-6, IL-10, and IFN-γ." (PMID 37511964, 2023).
lupus (continued). "Compared with healthy controls, patients with systemic lupus erythematosus (SLE) have higher serum levels of IFN-III, which is also correlated with the upregulation of inflammatory cytokines including IL-6, IL-27, Th17, and B cell activating factor (BAFF)." (PMID 37809098, 2023). "Considering B cells in the lupus kidney exhibited higher expression of SLC7A11, a downstreaming molecule mediated by the IL-6 in mediating ferroptosis resistance." (PMID 37273451, 2023). "An in vitro study on pristane-induced lupus BALB/c mice found that the use of S. baicalensis downregulated the production of proinflammatory cytokines such as TNF-α, IL-6, IL-10, and IFN-γ." (PMID 37511964, 2023). "The MSCs overexpressing IL-37 decreased the levels of IL-1, TNF-α, IL-17, IL-6, anti-dsDNA, and anti-ANA in systemic lupus erythematosus mice." (PMID 35935954, 2022). "The lupus-induced increase in interferon α (IFN-α), IL-6, and TNF-α levels was improved by resveratrol, as well as the renal manifestation, such as proteinuria." (PMID 35631330, 2022). "In FcgRIIb-/- lupus mice, LPS from gut leakage in synergy with BG induces prominent M1 pro-inflammatory macrophages partly through the induction of TNF-α and IL-6." (PMID 35897790, 2022). "In lupus-prone MRL/lpr mice, Artesunate decreased serum anti-dsDNA, improved renal function, and decreased renal injury and proteinuria along with renal Il6, Ifn, and Il21 mRNA." (PMID 35208225, 2022). "In MRL/lpr lupus-prone mice, another derivative, SM934, increased survival, decreased IL-6, IL-10, IL-12, and activated B cells and plasma cells, and lowered proteinuria, renal injury, BUN, and serum anti-dsDNA antibodies." (PMID 35208225, 2022). "Interestingly, the STAT/receptor coupling exhibited by IL-6/IL-27 was altered in patients with systemic lupus erythematosus (SLE)." (PMID 33871355, 2021). "In this study, these effects were demonstrated by decreased levels of circulating IL-6 and BAFF in lupus-prone mice, primarily originating from activated DCs." (PMID 34497607, 2021). "IL-38 increased expression levels of IL-6 and APRIL.IL-38 decreased lupus-like clinical symptoms histopathological features of skin and nephritis." (PMID 34539413, 2021). "In the pristane model of lupus, the inflammatory cytokines such as IFN-α, β and γ, IL-6, and IL-12 stimulate autoantibodies." (PMID 34705865, 2021). "Likewise, IL-6 blockade ameliorates lupus in mice and prevents anti-DNA autoantibody production whereas IL-6 concentration is elevated in SLE patients." (PMID 33746957, 2021). "Other proinflammatory mediators including IL-6 and IL-17 lead to TH17/Treg dysregulation in lupus patients compared to healthy individuals." (PMID 35069220, 2021). "The serum levels of IL-6, IFN-γ, IL-10, and IL-17A were higher in HCMVpp65422-439-immunized mice at 12 weeks post-immunization (24 weeks of age, lupus group) compared with NZB/W F1 mice treated with PBS (control group) or adjuvant only (adjuvant group)." (PMID 34824318, 2021). "In the control mice, prednisone showed significant therapeutic effects on lupus according to the decreases in ALT, Cr, LDH, anti-dsDNA, IFN-α, and IL-6." (PMID 32346376, 2020). "Here we demonstrated for the first time that increased IL-6 might be induced by impaired let-7f in SLE BM-MSCs, which might led to IL-6-STAT3-NF-κB pro-inflammatory circuit, and thus contribute to lupus development." (PMID 32133007, 2020). "This study suggested that serum IL-6 levels were higher in patients with SLE than in healthy controls, and they were positively correlated with disease activity when Systemic Lupus Erythematosus Disease Activity Index>4 was defined as active SLE." (PMID 33084768, 2020). "For example, classical NF‐κB signalling knockout in lupus‐prone mice strongly down‐regulated levels of IL‐1α, IFN‐γ and IL‐6 in the kidneys." (PMID 33079487, 2020).